GADD45G (growth arrest and DNA damage inducible gamma)
Description:
Involved in the regulation of growth and apoptosis. Mediates activation of stress-responsive MTK1/MEKK4 MAPKKK.
Synonyms: CR6; DDIT2; GADD45gamma; GRP17
Tractability: Small molecule: a structure with a bound ligand is known; it has a high-quality binding pocket.
Gene: Protein-coding gene on chromosome 9 (89,605,012 to 89,606,555, forward strand). Ensembl gene ENSG00000130222.
Gene Ontology:
Molecular function: protein binding
Biological process: positive regulation of apoptotic process; positive regulation of JNK cascade; positive regulation of p38MAPK cascade; positive regulation of cold-induced thermogenesis; regulation of cell cycle; positive regulation of MAPK cascade
Cellular component: cytoplasm; nucleus
Genetic constraint (gnomAD): Loss-of-function variants: 7 observed, 15.49 expected, observed/expected ratio (o/e) 0.45, 90% interval 0.26 to 0.85. The upper end of that interval is the gene's LOEUF score, 0.85, which puts it in group 3 of 6, group 1 being the genes least tolerant of losing a copy. Missense variants: 149 observed, 212.99 expected, observed/expected ratio (o/e) 0.7, 90% interval 0.61 to 0.8. Synonymous variants: 93 observed, 95.38 expected, observed/expected ratio (o/e) 0.98, 90% interval 0.82 to 1.16.
Homologues: Orthologues: chimpanzee GADD45G (99% identical), macaque GADD45G (99% identical), mouse Gadd45g (97% identical), pig GADD45G (97% identical), dog GADD45G (96% identical), rat Gadd45g (96% identical), rabbit GADD45G (90% identical), guinea pig GADD45G (82% identical), tropical clawed frog gadd45g (77% identical), zebrafish gadd45ga (67% identical), zebrafish gadd45gb.1 (65% identical), zebrafish GADD45G (44% identical), and 1 more. Paralogues in human: GADD45A (57% identical), GADD45B (56% identical).
Diseases named in the same sentence as GADD45G in open-access papers:
GADD45G is named in the same sentence as 92 diseases in open-access papers, as found by Europe PMC text mining. Sharing a sentence is not in itself a finding about the gene and the disease. The quoted sentences say what the papers report.
breast carcinoma (11 papers, 2011 to 2025). "Expression of GADD45G limits the metastasis and invasion of breast cancer cells, preventing tumor formation and breast cancer development in mice." (PMID 41007338, 2025). "In this study, GADD45G expression increased in human and mouse breast cancer cell lines treated with DOX and 2S-13." (PMID 41007338, 2025). "Our results indicated that GADD45g expression was increased in breast cancer cells infected with oHSV-1." (PMID 39850819, 2024). "It has been confirmed that GADD45G is abnormally expressed in various malignant tumors, such as esophageal cancer, breast cancer, and acute myeloid leukemia." (PMID 37833694, 2023). "Among the GADD45 family members, GADD45G is a functional tumor suppressor gene that is inactivated in different types of cancer cells, including breast cancer." (PMID 36135176, 2022). "FLAG-tagged human GADD45G (PB-GADD45G) and PB were transduced into breast cancer cell lines MCF7 and Hs578T, respectively." (PMID 34601500, 2021). "Enforced expression of GADD45G significantly inhibits tumor formation and breast cancer metastasis in mice through limitation of the propagation and invasion of breast cancer cells." (PMID 34601500, 2021). "Another point is that GADD45G significantly inhibits the migration and invasion of breast cancer cells." (PMID 34601500, 2021). "In this study, we found that Gadd45g is a direct target of miR-383, and miR-383 is able to increase the sensitivity of breast cancer cells to both UV irradiation and cisplatin treatment." (PMID 25415264, 2014). "GADD45G functions as a tumor suppressor in human breast cancers." (PMID 41007338, 2025). "GADD45G is a tumor suppressor that is involved in a host of cellular processes, including DNA repair, cell cycle arrest, and apoptosis, and its silencing or downregulation has been implicated in AML and breast cancer." (PMID 40188944, 2025). "High ERK protein expression levels have been shown to correlate with shorter survival in Triple-Negative Breast Cancer Patients, implying that there are other mechanisms excepted MAPK signaling responsible for effect of GADD45G on the development of breast cancer." (PMID 34601500, 2021). "Similarly, scratch experiments were used to evaluate the migration of cells, and the results demonstrated that GADD45G had an inhibitory effect on breast cancer migration." (PMID 34601500, 2021). "In addition, GADD45G plays as an antitumor gene and represses proliferation and migration of breast cancer cells in vivo and in vitro." (PMID 34601500, 2021). "Meanwhile, GADD45G functions as a suppressor in human breast cancers." (PMID 34601500, 2021). "Meanwhile, GADD45G plays a critical role in inhibiting breast cancer cell migration and invasion." (PMID 34601500, 2021). "We selected breast cancer cells to do further investigation, as the TCGA database analysis showed that GADD45G is highly expressed in breast cancer patients, implying that GADD45G may be an oncogene." (PMID 34601500, 2021). "In a breast cancer cell line resistant to farnesyltransferase inhibitors (FTI), (-)-Xanthatin was found to induce GADD45G, which subsequently activated p38 and JNK pathways, leading to decreased cell proliferation and caspase-independent apoptosis." (PMID 41018072, 2025). "Importantly, GADD45G suppresses growth and EMT of human breast cancer cells in vivo and vitro and acts as an antitumor character." (PMID 34601500, 2021). "The presence of miR-383 increased the cellular sensitivity to DNA damage in breast cancer cells, which was rescued by ectopic expression of Gadd45g without the 3′-UTR." (PMID 25415264, 2014). "Further, when Gadd45g cDNA lacking the 3′-UTR was overexpressed in breast cancer cells, the enhancement of cytotoxic agents-induced apoptosis by miR-383 was rescued indicating that the key target of miR-383 in regulating the sensitivity to genotoxic stress is Gadd45g." (PMID 25415264, 2014).
hepatocellular carcinoma (11 papers, 2007 to 2025). A malignant tumor that arises from hepatocytes. "GADD45G acts as a negative regulator of the Jak-Stat3 pathway and inhibits HCC by inducing cellular senescence; Deficient PDK4 expression promotes hepatocellular carcinoma cell proliferation, tumorigenicity, motility, and invasiveness." (PMID 40649911, 2025). "In human hepatocellular carcinoma cell lines, GADD45G expression strongly suppresses constitutive phosphorylation of STAT3 (Tyr705)." (PMID 38504984, 2024). "In hepatocellular carcinoma, Gadd45g elicited cellular senescence and suppressed tumor growth in vivo." (PMID 35211358, 2022). "Downregulation of Gadd45g contributes to the pathogenesis of hepatocellular carcinoma in both mice and humans." (PMID 32526449, 2020). "Our previous study has shown that the downregulation of growth arrest and DNA damage 45G (GADD45G) contributes to senescence bypass in hepatocellular carcinoma (HCC)." (PMID 26378039, 2015). "The ectopic expression of GADD45G induces senescence in hepatocellular carcinoma (HCC) cells and suppresses tumour growth in vivo." (PMID 26088100, 2015). "As Gadd45g-induced senescence in hepatocellular carcinoma cells depends on the activation of Stat3,27 we sought to determine whether an increase of Gadd45g reduced cell proliferation by repressing Stat3 activity." (PMID 35211358, 2022). "The present study explored the prognostic and predictive role of GADD45γ in hepatocellular carcinoma (HCC) treatment." (PMID 26172295, 2015). "Our previous studies have confirmed that GADD45G expression could be upregulated by 4-methoxydalbergione (4MOD) in liver cancer cells, but its potential pathological role in hepatocellular carcinoma (HCC) has not been fully understood." (PMID 37833694, 2023). "In line with our observation that ectopic GADD45G expression induces cell senescence and activates the p38 MAPK and JNK pathways, GADD45 proteins have been shown to induce cell cycle arrest at G2/M phase in HepG2 hepatoma cells, wherein the p38 MAPK and JNK act critically." (PMID 26378039, 2015).
acute myeloid leukemia (4 papers, 2021 to 2024). Acute myeloid leukemia (AML) is a group of neoplasms arising from precursor cells committed to the myeloid cell-line differentiation. "Our previous work demonstrates that GADD45g is preferentially silenced in patients with acute myeloid leukemia (AML) and its upregulation exerts selective and potent anti-leukemic effects." (PMID 38582902, 2024). "GADD45G is shown to be a novel tumour suppressor in acute myeloid leukaemia as a corresponding gene for DNA damage." (PMID 37559129, 2023).
glioma (4 papers, 2021 to 2025). A benign or malignant brain and spinal cord tumor that arises from glial cells (astrocytes, oligodendrocytes, ependymal cells). "We plan to establish a tissue microarray (TMA) resource based on clinical glioma samples and conduct qPCR or protein-level analyses to assess associations between GADD45G expression and tumor grade, subtype, and prognosis, providing stronger evidence for its clinical utility." (PMID 41018072, 2025). "GADD45G expression is significantly associated with glioma outcomes and may serve as a promising biomarker for prognosis evaluation." (PMID 41018072, 2025). "Additionally, five DDRGs (CDK4、HMGB2、WEE1、SMC3 and GADD45G) were selected to construct a DDRGs signature for glioma, stratifying patients into low- and high-risk groups." (PMID 34123852, 2021). "Therefore, investigating the role of GADD45G in glioma and its underlying mechanisms could uncover novel therapeutic targets, potentially enhancing the survival rate and clinical prognosis of glioma patients." (PMID 41018072, 2025). "To further investigate the biological effects of GADD45G overexpression in glioma cells, we performed CCK - 8 proliferation assays and Annexin V-FITC/PI double-staining flow cytometry to assess its impact on cell proliferation and apoptosis." (PMID 41018072, 2025). "To explore this further, we modulated GADD45G expression using plasmid overexpression, thereby confirming its tumor-suppressive role in glioma." (PMID 41018072, 2025). "In particular, comparisons across different histological types and WHO grades consistently showed that GADD45G expression was lower in GBM compared to lower-grade gliomas." (PMID 41018072, 2025). "Further experiments revealed that GADD45G modulates glioma cell invasion and migration, potentially through its effects on EMT-like phenotypic features." (PMID 41018072, 2025). "Our study uncovers the regulatory mechanism of tumor development mediated by GADD45G in glioma, offering a promising avenue for future research." (PMID 41018072, 2025). "In this study, we conducted a comprehensive analysis of gliomas using bulk and single-cell RNA sequencing data, and further explored the potential role of GADD45G in glioma progression through in vitro experiments." (PMID 41018072, 2025). "As anticipated, GADD45G overexpression led to a significant inhibition of glioma cell migration and proliferation." (PMID 41018072, 2025). "Western blot analysis was used to examine the role of GADD45G in glioma cell invasion and migration." (PMID 41018072, 2025). "Comprehensive analysis of multiple databases has revealed that GADD45G is highly expressed in glioma patients, suggesting its potential role as an oncogene." (PMID 41018072, 2025). "To assess the prognostic significance of GADD45G in glioma, we conducted a multivariate Cox regression analysis on TCGA-GBM data, categorizing patients into high-risk and low-risk groups based on their computed risk scores." (PMID 41018072, 2025). "Meanwhile, flow cytometry results demonstrated that GADD45G overexpression markedly increased the apoptotic rate in both cell lines, suggesting that GADD45G not only suppresses glioma cell growth but also induces apoptosis." (PMID 41018072, 2025). "A major limitation is the lack of validation using animal models or clinical tissue samples, which is essential for supporting the translational potential of GADD45G as a biomarker or therapeutic target in glioma." (PMID 41018072, 2025). "The forest map of Cox regression analysis indicated that SMC3 and GADD45G were positively correlated with the prognosis of patients with glioma, whereas CDK4, WEE1, and HMGB2 were negatively correlated with prognosis." (PMID 34123852, 2021). "We hypothesize that in low-grade gliomas, GADD45G upregulation may inhibit tumor progression, whereas, in malignant tumors, the suppression of GADD45G expression by tumor cells could contribute to tumor deterioration." (PMID 41018072, 2025).
glioma (continued). "While GADD45G dysregulation has been found in various cancers, its role in glioma is still unclear." (PMID 41018072, 2025). "To test this hypothesis, we conducted in vitro experiments where we overexpressed GADD45G in glioma cells." (PMID 41018072, 2025). "Although dysregulated expression of GADD45G has been observed in several human tumors, its role in gliomas remains unclear." (PMID 41018072, 2025). "Based on this conceptual framework, we next sought to investigate whether GADD45G influences EMT-like features in glioma cells through experimental validation." (PMID 41018072, 2025). "Based on this concept, we hypothesized that GADD45G might regulate glioma progression by modulating EMT-like features." (PMID 41018072, 2025). "The DDRGs signature composed of CDK4, HMBG2, WEE1, SMC3 and GADD45G could accurately predict the prognosis of gliomas." (PMID 34123852, 2021). "In terms of prognostic analysis, consistent with our previous results, high expression of CDK4, HMGB2, and WEE1 could lead to poor prognosis of glioma; however, gliomas with high expression of SMC3 and GADD45G were linked to longer survival." (PMID 34123852, 2021). "The results demonstrated that, across all datasets, higher GADD45G expression was significantly correlated with improved overall survival (OS) in both glioma and glioblastoma, suggesting that GADD45G may serve as a favorable prognostic biomarker for glioma patients." (PMID 41018072, 2025). "Notably, GADD45G expression is markedly reduced in glioblastoma relative to lower-grade gliomas." (PMID 41018072, 2025). "The study of the correlation between GADD45G expression and the infiltration levels of various immune cells suggests that it may influence the progression of glioma by affecting myeloid-derived suppressor cells, activated CD4 T cells, and CD56bright natural killer cells." (PMID 41018072, 2025). "Overexpression of GADD45G significantly inhibited the proliferation of A172 and SKMG1 glioma cells compared to the control group." (PMID 41018072, 2025). "We subsequently conducted cell-based experiments to determine whether GADD45G modulates EMT and thereby influences the invasive and metastatic behavior of glioma cells." (PMID 41018072, 2025). "Moreover, the gene expression level analysis by RT-qPCR suggested that among 10 DDR-related signature genes, HUS1, NUDT1, GADD45G, APEX1 and FAM175A were highly expressed in patients with glioma." (PMID 37086071, 2023). "In conclusion, although gliomas do not undergo canonical EMT, our data support that GADD45G plays a role in modulating EMT-like processes that contribute to tumor cell migration and invasion." (PMID 41018072, 2025). "Therefore, the observed relationship between GADD45G and EMT markers in our study is not indicative of classical EMT, but rather reflects a regulatory interaction within this EMT-like phenotypic modulation that is biologically relevant in glioma." (PMID 41018072, 2025).
esophageal cancer (3 papers, 2021 to 2025). A primary or metastatic malignant neoplasm involving the esophagus. "In esophageal cancer cell lines, GADD45G is silenced by promoter methylation, whereas GADD45A and GADD45B are not affected." (PMID 41018072, 2025). "Research indicates that the expression of GADD45G is frequently reduced in anaplastic thyroid carcinoma, gastric cancer, colorectal cancer, pancreatic cancer, non-Hodgkin lymphoma, Hodgkin lymphoma, nasopharyngeal carcinoma, cervical cancer, esophageal cancer, and lung cancer." (PMID 41018072, 2025).
IgA nephropathy (3 papers, 2019 to 2025). "We have previously shown that GADD45G mRNA expression in urinary sediment is associated with kidney disease progression in patients with IgA nephropathy." (PMID 39767752, 2024). "In the present study, we extend such findings by demonstrating that urinary GADD45G protein excretion was associated with kidney disease progression in patients with IgA nephropathy." (PMID 39767752, 2024). "With regard to IgA nephropathy, we have demonstrated that GADD45G mRNA expression in urinary sediment cells is associated with a decline in renal function." (PMID 39767752, 2024). "In conclusion, we showed that GADD45G protein excretion in urine was associated with worsening renal function in IgA nephropathy." (PMID 39767752, 2024). "In this study, we show evidence that urinary GADD45G protein is associated with the progression of IgA nephropathy." (PMID 39767752, 2024). "We also found that GADD45G was expressed in renal tubules across all pathologic grades, indicating that tubular damage was an early pathogenic process of IgA nephropathy." (PMID 39767752, 2024). "Taken together, it can be hypothesized that GADD45G is induced in renal tubular cells from the early pathogenic process of IgA nephropathy, which subsequently contributes to the occurrence of apoptosis of renal tubular cells, thereby leading to the worsening of renal function." (PMID 39767752, 2024). "GADD45γ has been shown to be related to GADD45γ nephritis, in which abnormally expressed GADD45γ protein leads to end-stage kidney disease and links to IgA nephropathy and mesangioproliferative glomerulonephritis." (PMID 40083548, 2025). "Immunohistochemistry showed extensive GADD45G staining in biopsies of all 45 IgA nephropathy patients." (PMID 39767752, 2024). "Immunohistochemistry showed that GADD45G was expressed across all pathologic grades of IgA nephropathy and mainly detected in the cytoplasm of renal tubules, whereas no staining was noted in normal tissues." (PMID 39767752, 2024). "Further studies are needed to establish the relationship between urinary GADD45G level and the progression of IgA nephropathy and define the role of GADD45G in the pathogenesis of IgA nephropathy." (PMID 39767752, 2024). "In the present study, GADD45G was identified in the cytoplasm of renal tubular cells of IgA nephropathy across all histological grades." (PMID 39767752, 2024). "Although GADD45G has shown potential as a biomarker in IgA nephropathy, there is currently limited research on whether its expression differs significantly by race or ethnicity." (PMID 39767752, 2024). "We reported that GADD45γ promotes renal fibrosis in unilateral ureteral obstruction (UUO), a model mimicking chronic renal injury, and is associated with progression of IgA nephropathy, suggesting that GADD45γ may promote progression of CKD." (PMID 30794682, 2019).
leukemia (3 papers, 2015 to 2017). A malignant (clonal) hematologic disorder, involving hematopoietic stem cells and characterized by the presence of primitive or atypical myeloid or lymphoid cells in the bone marrow and the blood. "In their study, they found that GADD45γ methylation was more frequent in leukemia and lymphomas (16%-88%) than solid tumors (11%-16%)." (PMID 25912017, 2015). "In our study, we tested several dysregulated genes associated with leukemia by microarray data analysis, including MPL, GADD45g, TOB1, SLA, and ETS1, and mainly focused on MPL, which was reduced by PARP-1 inhibition." (PMID 26314963, 2015). "Finally, it would be of interest to explore if overexpression of Gadd45a delays leukemia development, and whether other Gadd45 proteins (GADD45B and GADD45G) either separately or in combination with Gadd45a modulate CML development." (PMID 28086219, 2017).